NOX4 (NADPH oxidase 4)
Diseases named in the same sentence as NOX4 in open-access papers (continued):
Sharing a sentence is not in itself a finding about the gene and the disease.
cancer (215 papers, 2011 to 2026). A tumor composed of atypical neoplastic, often pleomorphic cells that invade other tissues. "Survival analysis, methylation analysis, and correlation studies were employed to assess the diagnostic and prognostic significance of NOX4 in diverse cancer types." (PMID 38663913, 2024). "The consequences of NOX4 methylation status varied across cancers, with hypermethylation positively associated with patient risk and correlated with shorter OS in bladder, kidney and endometrial cohorts." (PMID 38663913, 2024). "Intriguingly, hypermethylation of NOX4 is associated with a lower risk and longer OS in specific cancer cohorts, highlighting the complex interplay between epigenetic regulation and clinical outcomes." (PMID 38663913, 2024). "Further investigation into the correlation between NOX4 expression and immune checkpoint genes across 40 cancer types revealed a close association with common immune checkpoints, such as PD-L1 and CTLA-4." (PMID 38663913, 2024). "In summary, this study aims to elucidate the multifaceted role of NOX4 in cancer by exploring its diagnostic potential, prognostic significance, and impact on immune infiltration in tumors." (PMID 38663913, 2024). "In cancer-associated bone metastasis in a mouse model, upregulation of Nox4 results in elevated oxidization of skeletal muscle proteins, including RyR1." (PMID 38379095, 2024). "According to some research, high nuclear NADPH oxidase 4 expression is linked to cancer development and a bad prognosis in HCC." (PMID 37626693, 2023). "NOX4, a member of the NOXs family that produces reactive oxygen species, has been shown to be associated with the occurrence and development of many cancers." (PMID 36874093, 2023). "We thoroughly investigated the biological functions of NOX4 in cancerous tumors and the associated processes." (PMID 38012557, 2023). "Upregulation of NOX4 expression has been found to be strongly correlated with myofibroblastic cancer-associated fibroblasts (CAFs)." (PMID 35646942, 2022). "The nine studies included in this analysis, which involved a total of 2675 cancer patients, revealed an association between NOX4 expression and overall survival (OS)." (PMID 35265227, 2022). "Four studies with a total of 643 cancer patients revealed an association between NOX4 expression and disease-free survival (DFS) and recurrence-free survival (RFS)." (PMID 35265227, 2022). "A recent study showed that the inhibition of NADPH oxidase subunit NOX4 potentiates immunotherapy by preventing the formation of immunosuppressive phenotypes of cancer-associated fibroblast." (PMID 35086548, 2022). "The results implied an association between high expression of NOX4 and poor OS in cancer patients (HR: 1.31, 95% CI: 0.91–1.89, p = 0.15)." (PMID 35265227, 2022). "Further study is required to figure out the detailed mechanisms of PMCs, macrophages, and cancer cells in association with the NOX4–autophagy signaling axis." (PMID 33567693, 2021). "Not only is involved in a variety of physiological processes, NOX4 also mediates angiogenesis in pathological conditions which can cause cancer." (PMID 34930338, 2021). "Together, these data suggest that NOX4 expression is associated with aggressive cancer phenotypes, such as enhanced cell migration and dissemination, but not in regaining the epithelial phenotype." (PMID 33557266, 2021). "Recent studies showed NOX4 was closely associated with the occurrence and development of different cancers." (PMID 34930338, 2021). "NOX4 inhibition promotes the immunotherapy response by overcoming cancer-associated fibroblast-mediated CD8 T-cell exclusion." (PMID 34073426, 2021). "Nox2 and Nox4, located in lipid raft regions of the cell membrane, have been associated with growth promotion in cancer cells." (PMID 33585438, 2020).
cancer (continued). "Since it is a co-activator of the expression of the NADPH oxidase 4 (Nox4), an important factor in angiogenesis, cancer cells suffer from oxygen and nutrient deficiency due to its reduced expression in trichostatin A treated cells." (PMID 32582706, 2020). "NADPH oxidase enzymes (Nox1, Nox2, and Nox4), located in lipid rafts, have been found associated with growth promotion in cancer." (PMID 33585438, 2020). "For the abundant fibrous stroma observed in C4 subclass, anti-fibrosis drugs (like NOX4 inhibitor) suppressed the activation of cancer-associated fibroblasts and promoted the infiltration of CD8+ T cells, ultimately improving the efficacy of immunotherapy." (PMID 33680932, 2020). "Increased expression of NOX4 protein is associated with cancer progression and metastasis but the role of NOX4 in cell proliferation and invasion is not fully understood." (PMID 28099519, 2017). "Clinically, the expression of NOX-1 and NOX-4 in tumor was associated with poor survival and cancer relapse." (PMID 27642498, 2016). "Additionally, NOX4 expression was positively correlated with the infiltration abundance of cancer-associated fibroblasts (CAFs) in most tumors." (PMID 38663913, 2024). "However, the consistency of these findings across diverse cancer types and the underlying molecular mechanisms governing NOX4-mediated prognostic effects necessitate further exploration." (PMID 38663913, 2024). "Moreover, it has been revealed that neovascularization of cancer cells is caused by NOX4 dysfunction, which induces the vascular endothelial growth factor." (PMID 35265227, 2022). "However, through subgroup analyses, we also demonstrated that NOX4 expression is significantly associated with poor OS in gastrointestinal and other cancers and with poor DFS in other cancers." (PMID 35265227, 2022). "Furthermore, Nox4 signaling has been linked to pulmonary diseases as well as to various types of cancer." (PMID 35740059, 2022). "NOX4 played an important role in maintaining the phenotype of immunosuppressive cancer-associated fibroblasts (CAF) in tumors; immunotherapy could be enhanced by suppressing NOX4 to overcome CD8T cell rejection mediated by CAFs." (PMID 34983559, 2022). "Finally, a recent study reported that continuous NOX4-dependent ROS generation was required in cancer-associated fibroblasts (CAF) to maintain their activated phenotype, which promoted resistance to different immunotherapy modalities." (PMID 32630174, 2020). "Elevated NOX4 expression is a hallmark of several cancer types." (PMID 31083324, 2019). "Interestingly, stimulation of the IGF-1 receptor was positively associated with cell survival via induction of NOX4-generated ROS in a variety of cancers." (PMID 29065504, 2017). "Increased Nox4 is thought to increase sarcoplasmic reticulum (SR) Ca2+ leak by oxidizing the ryanodine receptor and lowering intracellular calcium, which has been shown to cause muscle weakness in aging and cancer cachexia." (PMID 27486747, 2016). "Consistent with previous studies on different hallmarks of cancer, oxidative stress is broadly engaged in cancer biology processes, and it has been suggested that the progression of bladder cancer may be associated with NOX-4 and lipid peroxidation (LPO) products resulting from oxidative stress." (PMID 39351147, 2024). "Therefore, the regulation of ROS production in the presence of increased FFA levels may be caused by ANGPTL4 secretion, which leads to NOX4 expression and cancer metastasis." (PMID 32641980, 2020). "Mitochondrial complex III and NADPH oxidases (NOX4) serve as the primary source of ROS during matrix detachment in cancer cells." (PMID 41596231, 2026).
cancer (continued). "Previous studies have shown that siRNA knockdown or pharmacologic inhibition of NOX4 promoted intra-tumoral CD8+ T-cell infiltration in many human cancer types and restored immunotherapy response induced by cancer-associated fibroblasts (CAFs)." (PMID 40463869, 2025). "The dual role of NOX4 in fibrosis and cancer underscores the importance of identifying candidates to such a treatment." (PMID 41516036, 2025). "The prognostic signature we have constructed includes TREX1, NOX4, and RRM2, with the latter two also being closely associated with cancer progression." (PMID 41346575, 2025). "In contrast, dysregulation of the NOX4 activity plays a detrimental role in various pathological conditions, including metabolic diseases, neurodegenerative diseases, and cancer." (PMID 40725005, 2025). "NADPH oxidase 4 (NOX4), a downstream mediator of the TGF-β signalling pathway, is strictly expressed in cancer-associated fibroblasts (CAF) of iCCA and acts in concert with NOX1 to regulate CAF functions." (PMID 40820091, 2025). "The multifaceted involvement of NOX4 in cancer underscores its significance as a potential target for further research and clinical exploration." (PMID 38663913, 2024). "It inhibits NADPH oxidase 4 (NOX4) and HIF1α, two key players in cancer cell survival, which in turn suppresses PKM2 and disrupts the Wnt/β-catenin signaling pathway-a critical process in cell proliferation." (PMID 39479443, 2024). "In cancer cells, mitochondrial ATP produced through oxidative phosphorylation limits NOX4 activity by binding to a specific ATP-binding motif in the C-terminal tail of NOX4, suggesting that NOX4 serves as an intracellular energy sensor." (PMID 39188529, 2024). "Studies suggest that targeting NOX4 as a potential druggable target to disrupt redox balance within cancer cells can inhibit cancer growth by mitigating the pro-tumorigenic effects associated with increased ROS production." (PMID 38663913, 2024). "In this study, our aim is to conduct an in-depth investigation of NOX4 across a range of cancer types to determine the relationship between NOX4 and tumors." (PMID 38663913, 2024). "Several studies have proposed a correlation between high NOX4 expression and adverse clinical outcomes, including reduced overall survival (OS) and disease-free survival in cancer patients." (PMID 38663913, 2024). "Understanding the relationship between NOX4 expression and immune infiltration is crucial for unraveling the immunomodulatory aspects of NOX4 in cancer progression." (PMID 38663913, 2024). "A comprehensive pan-cancer analysis of NOX4 expression was conducted using data from TCGA and GTEx cohorts." (PMID 38663913, 2024). "In conclusion, this comprehensive analysis deepens our understanding of NOX4 in cancer, highlighting its diverse roles in gene expression, diagnostic potential, prognostic implications, epigenetic regulation, functional associations, and immune." (PMID 38663913, 2024). "They found that NADPH oxidase 4 (NOX4) and YY1 expressions were positively linked to acquired resistance to EGFR-TKIs, while PD-L1, a downstream NOX4 target, ultimately contributed to immune escape in cancer cells." (PMID 38539569, 2024). "This implies a potential role for NOX4 in regulating immune checkpoint gene expression, suggesting its involvement in immune evasion mechanisms of cancer cells." (PMID 38663913, 2024). "Our findings suggested that KA-induced enhancement in PPARγ activity led to ER stress and apoptosis, which subsequently led to the upregulation of NOX4 in the treated cancer cells." (PMID 39770941, 2024). "As a member of the NADPH oxidase family, NOX4 plays a crucial role in the generation and regulation of ROS, making it a potential new target for cancer therapy." (PMID 38663913, 2024). "Multiple NOX members have been found to be dysregulated in multiple cancer models, with NOX4 being the most frequently expressed member." (PMID 37626693, 2023).
cancer (continued). "It is also imperative to thoroughly explore the role of NADPH oxidase 4 (NOX4) in the excessive levels of ROS in PTC lesions, given NOX4’s association with various forms of cancer." (PMID 37692064, 2023). "Other studies have also shown that NOX4 interacts with components of the actin cytoskeleton, and that knockdown of NOX4 using shRNA prevents wound closure in 4T1 cancer cells." (PMID 36776559, 2023). "NOX4-mediated metabolic reprogramming including an increase in PKM2 expression, proving that NOX4 plays the key role of mitochondrial energetic sensor and fulfils the function of metabolic checkpoint, coupling the metabolic switch to cancer cell survival." (PMID 36768405, 2023). "A few studies demonstrate that NOX4 promotes cell growth through cell cycle regulation and apoptosis suppression, even if the methods through which NOX4 influences the proliferation, invasion, and survival of cancer cells are still unclear." (PMID 38012557, 2023). "NOX4-induced ROS production was also found to be involved in various oncogenic signaling pathways in cancer." (PMID 37044213, 2023). "Further, Nox4 allows for oncogenic adaptation in cancer by facilitating a metabolic shift that is less dependent on aerobic conditions." (PMID 37628627, 2023). "The perinuclear localization of NOX4 observed in malignant human thyroid tissues is concordant with this, as genomic instability is a characteristic of malignant tumors." (PMID 37504283, 2023). "Emerging reports suggest that NADPH oxidase Nox4 is a powerful regulator for ROS release, and the Nox4-ROS pathway regulates cell survival and cell death in cancer." (PMID 36982736, 2023). "It has been reported that NADPH-oxidase family members, in particular NOX1 and NOX4, are expressed by cancer cells and promote tumor growth and metastasis in several cancers (i.e., melanoma, gastric, pancreatic, and colorectal cancers)." (PMID 38137406, 2023). "NOX4 activates metabolic pathways related to tumor development; it regulates the ROS production of cancer cells." (PMID 36614301, 2023). "With a 95% confidence interval, a pooled odd ratio (OR) was used to calculate the relationship between NOX4 expression patterns and cancer metastasis." (PMID 38012557, 2023). "The chain reaction between H2O2 and NOX4 that is initiated by hypoxia seems to make NOX4 a key player in ROS generation in cancer." (PMID 36613455, 2022). "The aim of this review is to provide a synopsis of our current knowledge concerning NOX4-related processes in the oncogenic metabolic adaptation of cancer cells." (PMID 35269843, 2022). "Many recent studies have shown that NOX4 and generated ROS are related to cancer development, proliferation, invasion, epithelial-to-mesenchymal transition, and metastasis." (PMID 35265227, 2022). "In fact, cancer cells ubiquitously up-regulate the expression of NOX4, and the up-regulated NOX4 enhances the production of ROS." (PMID 36613455, 2022). "An increase in NOX4 expression in response to the exposure to model oxidized DNA fragments was previously observed for MCF7 cancer cells, HUVEC endothelial cells and mesenchymal stem cells of human adipose tissue." (PMID 36553550, 2022). "Concerning NOX-mediated signaling, Nrf2 mediates redox adaptation in NOX4-overexpressed non-small cell lung (NSCL) cancer cells." (PMID 35269843, 2022). "Increased expression of the NOX4/p22phox complex in cancer has been previously reported, which activates angiogenesis and metastasis." (PMID 36199546, 2022). "The NOX4 activity can be potentiated by hypoxia and consequently, the production of ROS, which can contribute to cancer malignancy." (PMID 36290761, 2022). "Taken together, NOX4, involved in a variety of biological process in cancers, has promising prospective awaiting for further exploration." (PMID 35646942, 2022). "The relationship between NOX4 and cancer has been demonstrated, and enhanced ROS generated from NOX4 are known to promote cancer cell proliferation, migration, and metastasis." (PMID 35265227, 2022).
cancer (continued). "NOX4 is upregulated in several types of human cancers, such as melanoma, ovarian, prostate, colorectal, and bladder cancer." (PMID 35682803, 2022). "Given that NOX4 functions as an energetic sensor coupling cancer metabolic reprogramming to drug resistance, we then assumed that NOX4 contributes to the acquisition of drug resistance in starved PTC cells." (PMID 35396551, 2022). "Several NOX members have been found to be dysregulated in diverse cancer models, with NOX4 being the member most frequently expressed." (PMID 35646942, 2022). "In this review, we primarily discussed the biological function of NOX4 in tumorigenesis and progression of multiple cancer models, including its role in activating oncogenic signaling pathways, rewiring the metabolic phenotype and mediating immune response." (PMID 35646942, 2022). "siRNA-mediated knockdown of NOX-4 abolished the upregulation of several metabolic enzymes involved in cancer cell adaptation." (PMID 35269843, 2022). "Unrestrained NOX4 activity has been described in diverse cancers, and NOX4 is now considered as a driving force in several cancer types." (PMID 35269843, 2022). "Recent studies have shown that nicotinamide adenosine dinucleotide phosphate oxidase 4 (NOX4) is related to cancer development, proliferation, invasion, epithelial-to-mesenchymal transition, and metastasis." (PMID 35265227, 2022). "In this study, we first evaluated the prognostic and clinicopathological value of NOX4 expression in cancer patients." (PMID 35265227, 2022). "In Ras-driven cancer cells, abnormal mitochondria and activated NOX4 boost ROS-dependent cell proliferation." (PMID 35799889, 2022). "Firstly, tumors are complex identities constituted of cancer cells, capillaries, connective tissue, and immune cells, and NOX4-related redox pathways affect their functioning with different and often opposing pro- or anticancer outcomes." (PMID 35269843, 2022). "This review assembles recent data on redox signaling in the adaptation of cancer cell metabolism with a specific focus on the role of NOX4 in these processes." (PMID 35269843, 2022). "Precious studies have clearly introduced NOX4 as a key regulator of cancer occurrence and development in multiple cancer models." (PMID 35646942, 2022). "Currently, the precise mechanism of NOX4-related oncogenesis in diverse cancer types is incompletely understood and is the focus of intensive research efforts." (PMID 35269843, 2022). "Appropriate studies were collected by searching the PubMed, EMBASE, and Cochrane library databases, and the prognostic value of NOX4 expression in cancer patients was assessed through a meta-analysis." (PMID 35265227, 2022). "Nevertheless, in the present study, we reported a systematic review of the relationship between NOX4 expression and prognosis in cancer patients." (PMID 35265227, 2022). "Presumably, NOX4 is the main oxidative stress factor in a number of diseases such as cardiovascular diseases and cancer." (PMID 35696356, 2022). "Specific inhibition of both NOX-4 and NOX-2 alleviates increased cancer risk in A-T null mice, whilst the inhibition of ATM increased NOX-4 expression in normal cells." (PMID 33868575, 2021). "The invasive property of cancer cells is enhanced in hydrogen peroxide-inducible clone-5 (HIC-5) knockdown by increased stability of MMP9 mRNA via NADPH oxidase 4 (NOX4) mediated mtROS." (PMID 35186947, 2021). "Among them, NOX4 is the most frequently overexpressed isoform in cancer cells and has been shown to promote NSCLC cell proliferation and metastasis." (PMID 33980809, 2021). "In renal cell carcinoma, NOX4 acts as a mitochondrial energetic sensor coupling cancer metabolic reprogramming with drug resistance." (PMID 34257808, 2021).